ARIH2OS (ARIH2 opposite strand lncRNA)
Synonyms: C3orf71
Gene: Long non-coding RNA gene on chromosome 3 (48,917,788 to 48,919,385, reverse strand). Ensembl gene ENSG00000221883.
Subcellular location: Membrane